ENSG00000301168 (novel transcript)
Gene: Long non-coding RNA gene on chromosome 7 (25,260,026 to 25,288,735, reverse strand). Ensembl gene ENSG00000301168.
Gene Ontology:
Biological process: RNA processing
Cellular component: nucleolus